TRAF6 (TNF receptor associated factor 6)
Diseases named in the same sentence as TRAF6 in open-access papers (continued):
Sharing a sentence is not in itself a finding about the gene and the disease.
cervical carcinoma (12 papers, 2014 to 2025). A carcinoma arising from either the exocervical squamous epithelium or the endocervical glandular epithelium. "In view of our previous observation that blockade of ubiquitination on TRAF6 by DRAK1 was a key mechanism regulating TRAF6 stability in cervical cancer cells, targeting TRAF6 E3 ligase activity associated with drug resistance in other cancers deserve further investigation." (PMID 35194034, 2022). "Collectively, these results suggest that a decrease in DRAK1 protein level is associated with paclitaxel resistance in cervical cancer cells and results in an increase in TRAF6 expression and TRAF6-mediated NF-κB activation, promoting tumorigenesis of paclitaxel-resistant cells." (PMID 35194034, 2022). "Previous studies have demonstrated the oncogenic role of TRAF6 in various cancers and the upregulation of TRAF6/NF-κB axis conferred chemoresistance of cancer cells, however, the function of TRAF6 in association with paclitaxel resistance in cervical cancer has remained unclear." (PMID 35194034, 2022). "In cervical cancer, miR-146a also has an increased level and a tumor-promoting role, which it exerts by inhibiting IRAK1 and TRAF-6 (TNF-receptor-associated factor 6) and stimulating Cyclin-D1." (PMID 39057062, 2024). "MiR-146a regulates Th17 cell differentiation through NF-κB signaling by targeting TRAF6, impacting cervical cancer cell growth and apoptosis." (PMID 38169510, 2024). "Another study uncovered that growth inhibition by quinine treatment in lung adenocarcinoma and cervical cancer cell lines is due to the impaired activity of TRAF6, a key regulator of Akt signaling." (PMID 37529110, 2023). "Our previous study revealed that depletion of DRAK1 enhances the protein expression levels of TRAF6, eventually activating NF-κB signaling and promoting tumorigenesis and lung metastasis in cervical cancer cells." (PMID 35194034, 2022). "In this study, we investigated that a decreased DRAK1 protein stability followed by upregulation of TRAF6 levels, and TRAF6-mediated NF-κB signaling pathway, promotes the malignancy of paclitaxel-resistant cervical cancer cells." (PMID 35194034, 2022). "The expression of miR-146a can downregulate the expression of receptor-related kinase 1 (IRAK1) and TNF receptor-related factor 6 (TRAF6), promote the expression of cyclin D1, and promote the occurrence of cervical cancer." (PMID 33967611, 2021). "miR-146a was not only overexpressed in cervical cancer and promoted cancer cell proliferation by targeting TRAF6 through NF-κB signaling, but also in oral carcinoma by targeting IRAK1, TRAF6, and NUMB." (PMID 33015045, 2020). "Although it is already known that NF-κB activation by anticancer agents leads to the chemoresistance of cancer cells, the function of TRAF6 associated with drug resistance in cervical cancer has not been elucidated." (PMID 35194034, 2022). "Forced expression of DRAK1 in cervical cancer cells with acquired resistance to paclitaxel decreased cell growth and tumorigenesis of paclitaxel-resistant cells as well as cellular resistance to paclitaxel by downregulating TRAF6 expression and NF-κB activation." (PMID 35194034, 2022). "In cervical cancer, recent studies have showed that DRAK1 is identified as a novel antagonist of inflammation that targets TRAF6 for degradation, thereby limiting the progression of advanced cervical cancer mediated by inflammatory signaling." (PMID 40521202, 2025). "In other urogenital cancers, such as advanced cervical cancer, DRAK1 suppresses pro-inflammatory signaling by promoting TRAF6 degradation, thereby inhibiting inflammatory signaling-mediated tumor growth and metastasis." (PMID 38169510, 2024). "miR-146a possesses potential to promote cervical cancer cell viability through modulation of IRAK1 and TRAF6." (PMID 35799607, 2022). "Furthermore, miR-146a can enhance the viability of cervical cancer cells through regulating IRAK1 and TRAF6." (PMID 35799607, 2022).
cervical carcinoma (continued). "Western blot results showed that IgG did not affect the protein levels of MyD88, IRAK1, and TRAF6 (data not shown), indicating that TLR4 was at least the major target involved in IgG-mediated positive regulation of LPS-induced proinflammatory cytokine production in cervical cancer cells." (PMID 25179302, 2014).
myelodysplastic syndrome (12 papers, 2016 to 2025). A clonal hematopoietic disorder characterized by dysplasia and ineffective hematopoiesis in one or more of the hematopoietic cell lines. "Tifab (TRAF-interacting protein with forkhead-associated domain B) has been manifested to regulate hematopoiesis through Toll-like receptor (TLR)-TRAF6 complex and loss of Tifab induces BM failure and myelodysplastic syndrome (MDS)." (PMID 35740994, 2022). "Increased TRAF6 signaling is linked to myelodysplastic syndrome (MDS), where TRAF6 overexpression in mouse HSPCs results in MDS-like features, such as cytopenia, by regulating exon specification through TRAF6-mediated ubiquitination of RNA-binding protein hnRNPA1." (PMID 38609495, 2024). "Silencing of TRAF6 has been reported to enhance the effect of bortezomib in MM and acute myeloid leukaemia/myelodysplastic syndrome." (PMID 30736330, 2019). "It has been reported that bortezomib can induce proteasome independent degradation of TRAF6 in myelodysplastic syndrome." (PMID 29703234, 2018). "Ectopic TRAF6 leads to myelodysplastic syndrome and facilitates fatal acute myeloid leukemia in primary bone marrow cells in mice." (PMID 27791197, 2016). "Therefore, TRAF6 is assumed to play a pivotal role in myeloid malignancies, including myeloproliferative neoplasms, acute myeloid leukemia, myelodysplastic syndromes, and related precursor cell neoplasms." (PMID 38169510, 2024). "Interestingly, TRAF6 is overexpressed in HSC from myelodysplastic syndrome (MDS) patients as compared to healthy individuals, and chronic innate immune signaling via TRAF6 has been implicated in hematopoietic defects associated with MDS." (PMID 33224133, 2020). "Furthermore, a reduced TRAF6 protein level was found in bortezomib-induced autophagy and subsequent cytotoxicity in myelodysplastic syndrome/acute myeloid leukemia." (PMID 29703234, 2018). "miR-146a has been previously identified as an important regulator of myeloid differentiation in the context of myelodysplastic syndrome (MDS), where it targets TRAF6." (PMID 28399410, 2017).
acute myeloid leukemia (11 papers, 2016 to 2026). Acute myeloid leukemia (AML) is a group of neoplasms arising from precursor cells committed to the myeloid cell-line differentiation. "The dysplastic phenotype in TRAF6-transduced mice is linked to IL-6 overexpression and paracrine action, while clonal expansion and acute myeloid leukemia (AML) development rely upon TRAF6 activation in a cell-autonomous fashion." (PMID 36428749, 2022). "PSMA1, an α-ring component involved in the proteolytic degradation of most intracellular proteins, is downregulated by autophagic lysosome-induced TRAF6 degradation to inhibit the proteasome and result in apoptosis in acute myeloid leukemia." (PMID 34689164, 2021). "Although altered TRAF6 expression is observed in human acute myeloid leukemia (AML), its role in the AML pathogenesis remains elusive." (PMID 38609495, 2024). "In the mouse model of acute myeloid leukemia (AML), IFN-γ receptor 1 (IFNGR1) suppression can decrease the expression of PD-L1 through the MEK/ERK and MYD88/TRAF6 pathways." (PMID 39343796, 2024).
Arthritis (11 papers, 2011 to 2024). Inflammation of a joint. "Increase systemic bone mass via inducing the reprogramming of osteoclasts metabolism, enhancing glycolysis, and down-regulating TRAF6 and NFATc1;Prevent bone loss after menopause;Alleviate arthritis." (PMID 36140990, 2022). "As a result, Treg-specific TRAF6-deficient mice develop various diseases such as allergic skin diseases, arthritis, and lymphadenopathy." (PMID 33294443, 2020). "This study has shown that miR-146a KO mice suffer more severe gouty arthritis than WT mice and has indicated that miR-146a-deficient mice lose the repression of TRAF6 and IRAK1, leading to enhanced production and secretion of pro-IL-1β." (PMID 29544526, 2018). "Treg-specific TRAF6-deficient (cKO) mice developed allergic skin diseases, arthritis, lymphadenopathy and hyper IgE phenotypes." (PMID 24058613, 2013). "Our suspicion that the elevation in TRAF6 in NC monocytes supports increased osteoclastogenesis is in keeping with data from a murine arthritis model (hTNFtg)." (PMID 32765497, 2020). "In vivo, the inhibition of TRAF6 using mice-specific TRAF6 siRNA inhibit serum anti-collagen II antibodies, MMP-1, MMP-3, and MMP-9, thereby reducing the severity of arthritis and joint inflammation." (PMID 33294443, 2020). "Studies have further found that Treg-specific TRAF-6 knockout (CKO) mice may develop allergic skin diseases, arthritis, swollen lymph nodes and a hyper immunoglobulin E phenotype." (PMID 28219358, 2017). "After IFN-β administration, the arthritis scores were decreased; synovial inflammation, cartilage, and bone destruction were clearly attenuated; and the expression of c-Fos and NFATc1 were reduced, while RANKL and TRAF6 expression was unchanged." (PMID 25491303, 2014).
asthma (11 papers, 2020 to 2024). "miR-125b-5p is significantly over-expressed in asthma, and AK089514–miR-125b-5p–TRAF6 axis play critical role in asthma by modulating macrophage polarization." (PMID 36717790, 2023). "High expression of TRAF6 would activate the NF-κB pathway, which ultimately leads to the chronic inflammation and asthma." (PMID 35859797, 2022). "qRT-PCR and western blot uncovered that TRAF6 mRNA and protein levels in asthma cells transfected with miR-146a-5p mimics were greatly declined, and transfection of miR-146a-5p inhibitors functioned oppositely." (PMID 34002665, 2021). "Collectively, we concluded that miR-146a-5p/TRAF6 axis is a crucial mechanism of asthma pathogenesis." (PMID 34002665, 2021). "We report that miR-146a-5p is implicated in regulating airway inflammation and the injury of airway epithelial cells in asthma via targeting TRAF6." (PMID 34002665, 2021). "It is reported that miR-146a restrains the secretion of IL-33 in type II innate lymphoid cells by blocking IRAK1 and TRAF6 expression, thus inhibiting airway inflammation in asthma." (PMID 34002665, 2021). "miR-146a mimics attenuate allergic airway inflammation by impacting ILC2 via IRAK1/TRAF6 pathways, while miR-146a inhibitors attenuate asthma via activating TLR2-signaling pathways in inflammatory monocytes." (PMID 32600285, 2020). "Overall, these results indicated that targeting the sNASP/TRAF6 axis in asthma might be a protective mechanism partly by reducing mucin overproduction in asthmatic airways." (PMID 36012669, 2022). "Collectively, miR-146a-5p may protect airway epithelial cells and inhibit the pathogenesis of asthma via targeting TRAF6." (PMID 34002665, 2021). "To delve into the potential mechanism of miR-146a-5p in asthma, we predicted the potential downstream targets of miR-146a-5p by StarBase database and observed that there was a complementary binding site between miR-146a-5p and TRAF6 mRNA 3'UTR." (PMID 34002665, 2021). "Overall, this study shows that miR-146a-5p inhibits the pathogenesis of asthma by targeting TRAF6." (PMID 34002665, 2021). "In addition, the downstream effector of miR-146a-5p, including TNF receptor-associated factor 6 (TRAF6) and TIR domain-containing adaptor protein (TIRAP), which are related to airway epithelial cell injury and airway inflammatory response in asthma, were decreased." (PMID 37090722, 2023). "Treatment with the PEP-NASP peptide, a selective TRAF6-blocking peptide, ameliorated HDM-induced asthma in mice." (PMID 36012669, 2022). "In conclusion, miR-146a-5p ameliorates the inflammatory response and epithelial barrier injury of HSAECs via targeting TRAF6 and repressing MAPK pathway, by which it can inhibit the development of asthma." (PMID 34002665, 2021). "MiR-146-5p targets inflammatory mediators like COX2, IL-1β, KIT, NFKB1, TLR4, TRAF6, and UHRF1 and has been proposed as a predictor for asthma exacerbations in childhood asthma." (PMID 32998415, 2020). "In conclusion, this study indicated that the sNASP/TRAF6 axis plays a regulatory role in asthma by modulating mucus overproduction, and the PEP-NASP peptide might be a potential target for asthma treatment." (PMID 36012669, 2022). "Since the sNASP/TRAF6 axis is critical for in vitro MUC5AC production, we evaluated the effect of the PEP-NASP peptide on mucus hypersecretion in vivo using an HDM-induced asthma model." (PMID 36012669, 2022). "Flow cytometry proved that overexpression of TRAF6 facilitated PAF-induced apoptosis and weakened the impact of overexpression of miR-146a-5p on apoptosis, indicating that miR-146a-5p can reduce airway inflammation and cell barrier damage in asthma by targeting TRAF6." (PMID 34002665, 2021). "Therefore, despite evidence from experimental studies, the effect of miR-223 on the target genes IKKα, TRAF6, and CUL1 in asthma and COPD patients, and whether their regulation contributes to the pathogenesis of these diseases, remains unclear." (PMID 32509795, 2020).
cardiac hypertrophy (11 papers, 2016 to 2025). "Taken together, these in vivo gain- and loss-of-function studies demonstrate that elevated cardiac Traf6 expression is essential for the development of the pathological cardiac hypertrophy induced by chronic pressure overload." (PMID 27249171, 2016). "Cardiac-specific Traf6 overexpression exacerbates cardiac hypertrophy in response to pressure overload or angiotensin II (Ang II) challenge, whereas Traf6 deficiency causes an alleviated hypertrophic phenotype in mice." (PMID 27249171, 2016). "Taken together, the increased TRAF6/Traf6 expression in heart samples with cardiac remodelling suggests that TRAF6 may be implicated in the pathogenesis of cardiac hypertrophy." (PMID 27249171, 2016). "E3 ligases, which determine substrate specificity in ubiquitination, are increasingly recognised for their role in pathological cardiac hypertrophy, with ligases such as TRAF6, TRIM16 and WWP1 being identified as key contributors." (PMID 40753540, 2025). "In their study, TRAF6 regulated pathological cardiac hypertrophy dependent on directly interacting with TAK1 and promoting TAK1 ubiquitination." (PMID 32210723, 2020). "Regulation of pathologic cardiac hypertrophy by TRAF6 is possible via regulating TAK1-JNK1/2-p38 signaling pathway." (PMID 30186311, 2018). "Whereas, the downregulation or complete deletion of TRAF6 alleviated cardiac hypertrophy and cardiac dysfunction along with a decrease in expression levels of hypertrophy markers." (PMID 30186311, 2018). "The cardiac hypertrophy stimulants, such as Ang II and phenylephrine, can increase the expression of TRAF6 in cardiomyocytes as well as in the heart tissue." (PMID 30102008, 2018). "The present study reveals the previously unrecognized biological function of TRAF6 in cardiac hypertrophy." (PMID 27249171, 2016). "The combined in vivo and in vitro experiments clearly validated an essential role for Traf6 during the initiation and progression of pathological cardiac hypertrophy." (PMID 27249171, 2016). "In response to pressure overload, Traf6 overexpression significantly aggravated cardiac hypertrophy, as evidenced by increased ratios of heart weight (HW) to body weight (BW), lung weight (LW) to BW and HW to tibial length (TL)." (PMID 27249171, 2016). "Taken together, these data indicate that the activation of TAK1-JNK1/2/p38 signalling appears to be essential for TRAF6-mediated cardiac hypertrophy." (PMID 27249171, 2016). "Collectively, these results indicate that the upregulated Traf6 levels in the heart promote pressure overload-induced cardiac hypertrophy and the resultant heart dysfunction." (PMID 27249171, 2016). "Based on various in vivo and in vitro cardiac hypertrophy models, we clearly identified cardiac TRAF6 as a positive regulator of functional and structural cardiac remodelling via activating TAK1-JNK1/2/p38 signalling." (PMID 27249171, 2016). "The structural and functional remodelling of the heart induced by Ang II infusion were significantly exacerbated by Traf6 overexpression, whereas Traf6-CKO mice displayed markedly alleviated cardiac hypertrophy and dysfunction." (PMID 27249171, 2016). "Taken together, we define TRAF6 as an essential molecular switch leading to cardiac hypertrophy in a TAK1-dependent manner." (PMID 27249171, 2016). "Our functional studies provided robust evidence that the increased Traf6 expression induced by ROS production positively regulates the development of pathological cardiac hypertrophy." (PMID 27249171, 2016). "Previous research has demonstrated that reactive oxygen species generated during cardiac hypertrophy progression can induce the auto-ubiquitination of TRAF6, leading to the recruitment of TAB2 and the subsequent binding to TAK1, thereby activating the TAK1-mediated prohypertrophic signaling pathway." (PMID 40880411, 2025).